SDC4 (syndecan 4)
Diseases named in the same sentence as SDC4 in open-access papers (continued):
Sharing a sentence is not in itself a finding about the gene and the disease.
melanoma (20 papers, 2013 to 2025). A malignant, usually aggressive tumor composed of atypical, neoplastic melanocytes. "Imbalances in SDC4 expression have also been linked to melanomas, liver carcinomas and mesotheliomas." (PMID 36152082, 2023). "Recent findings document not only a role for syndecan-4 in lymphangiogenesis, but also in classical VEGFA-mediated angiogenesis: Syndecan-4-deficient mice show reduced angiogenesis not only in a model of diabetic retinopathy, but also in a melanoma model of tumor angiogenesis." (PMID 33810567, 2021). "Other studies described the role of syndecan 4 in mechanosignaling pathways of melanoma, glioblastoma, and osteosarcoma cells." (PMID 39334952, 2024). "Remarkably, integrins and syndecan 4 form a trimolecular complex with Thy-1, where two triads have been reported: α5β1/Thy-1/syndecan 4 in melanoma/endothelial cells and αvβ3/Thy-1/syndecan 4 in a neuron/astrocyte model." (PMID 35186924, 2022). "More specifically, trans-interaction between Thy-1 and integrin, which also involves the heparan sulfate proteoglycan syndecan-4 forms a tri-molecular complex that regulates the adhesion and migration of melanoma cells, blood cells and astrocytes." (PMID 35733855, 2022). "In fact, the triple cooperation between Thy-1, syndecan-4, and α5β1 integrin is responsible for mediating the contractility response to mechanosignals in melanoma cells." (PMID 33669066, 2021). "Of note, syndecan-4 is required for the activating function of latent heparanase in the activation of VLA4 integrin in melanoma cells." (PMID 33810567, 2021). "SDC4 silencing increases the migration, whilst SDC4 overexpression decreases the migration of melanoma cells." (PMID 34282767, 2021). "Along with beta 3 integrin and WNT5A, syndecan-4 is part of a gene signature characteristic for metastatic disease in melanoma." (PMID 33810567, 2021). "SDC3 and SDC4 genes expression levels were the highest on melanoma cells and were also present on macrophages and endothelial cells but absent on B and T cells." (PMID 33117401, 2020). "A ternary complex formed by SDC4, α5β1 integrin, and endothelial surface glycoprotein Thy-1 supporting cell-cell adhesion modulates mechano-signaling in melanoma cells." (PMID 32916872, 2020). "Mechanistically, it was described that FGF2 drives melanoma cell migration through a syndecan-4 and focal adhesion kinase-dependent mechanism." (PMID 29235576, 2017). "Thy-1 forms a tri-molecular complex with α5β1 integrin and syndecan-4 and supports β1 integrin- and syndecan-4-mediated mechanosignaling in melanoma cells." (PMID 28744021, 2017). "Together, these data indicate that syntenin-1 negatively regulates syndecan-4-mediated anti-tumorigenic activity in melanoma cells." (PMID 27830760, 2016). "Here, we report for the first time that the syndecan-4/syntenin-1 interaction via syntenin-1 dimerization critically regulates melanoma cell migration and metastasis." (PMID 27830760, 2016). "Syndecan-4, which acts as a tumor suppressor by regulating tumorigenic activities, is expressed in melanoma cells." (PMID 27830760, 2016). "Overexpression of syndecan-4 significantly reduced the migration of A375 melanoma cells, whereas siRNA-mediated reduction of syndecan-4 expression enhanced the migration of these cells." (PMID 27830760, 2016). "To first assess the role of syndecan-4 in melanoma cells, we examined the effects of syndecan-4 expression on melanoma cell migration." (PMID 27830760, 2016). "On the other hand, CD90 binds to αvβ3 integrin in trans by syndecan-4 and leads to focal adhesion formation in melanoma invasion." (PMID 26556861, 2015). "FGF-2 treatment of melanoma cells resulted in the reduction in syndecan-4 expression and downregulation of FAK Y397-phosphorylation thus decreasing cell attachment on FN and promoting their migration." (PMID 23844358, 2013).
melanoma (continued). "Arf6 expression was suppressed in A2780 ovarian carcinoma cells and A375-SM malignant melanoma cells, which both use α5β1, αVβ3, and syndecan-4 to engage fibronectin, and in both cell lines Arf6 inhibition blocked recycling of α5β1 but not αVβ3." (PMID 23453597, 2013). "Similarly, human SDC4 favors cell migration and invasion through activation of Wnt5A signals in melanoma, indicating conserved signaling downstream of this proteoglycan in NC cell migration and malignant progression of an NC-derived cancer." (PMID 38634469, 2024). "Indeed, syndecan-4 is an important component of the Wnt5A autocrine signaling loop and its overexpression is correlated to increased metastatic potential in melanoma patients." (PMID 33810567, 2021). "FGF-2 regulates melanoma cell migration in a SDC4-dependent manner." (PMID 34282767, 2021). "Syndecan-4 and α5β1 integrin also cooperates to activate PKCα in melanoma cells." (PMID 33669066, 2021). "However, SDC4 is overexpressed in melanoma, liver cancer, ovarian carcinoma, mesothelioma and fibrosarcoma." (PMID 34282767, 2021). "Notably, binding of the cell-penetrating peptide Xentry to syndecan-4 has been utilized to target therapeutics to melanoma cells in vitro." (PMID 33810567, 2021). "Moreover, invasive growth of melanoma cells can be inhibited by syndecan-4 knockdown and rescued by addition of Wnt5a, suggesting an impact of syndecan-4 on this signaling pathway in melanoma." (PMID 33810567, 2021). "However, no previous study has reported a comprehensive analysis of the potential crosstalk between syntenin-1 and syndecan-4 in melanoma." (PMID 27830760, 2016). "Syndecan-4 is also known to mediate the invasion and metastasis of melanoma cells." (PMID 27830760, 2016). "Syndecan-4 potentiates Wnt5a signaling and enhances invasion and metastasis of melanoma cells." (PMID 23844358, 2013). "Regarding melanoma progression, FGF-2 modulates melanoma migration capacity through a syndecan 4-dependent mechanism." (PMID 39334952, 2024). "In melanoma cells, GPNMB attenuates the activation of T cells that are activated via syndecan-4, allowing the evasion of melanoma cells from immunological recognition and destruction." (PMID 38822058, 2024). "The matricellular protein cysteine-rich angiogenic inducer 61 (Cyr61) interacts with SDC4, activates integrins and induces metastasis formation, migration and tumorigenicity in MV3 human melanoma cells." (PMID 34282767, 2021). "The tumor suppressor role of SDC4 was also shown in vivo as the overexpression of SDC4 resulted in decreased pulmonary metastatic potential and decreased lymph node metastasis of B16F10 melanoma cells in mice." (PMID 34282767, 2021). "In order to examine the expression of Sdc-3 and Sdc-4 in the TME, we analyzed single-cell RNA sequencing (scRNA-seq) data from melanoma patients, which was the solid tumor type with the highest ratio of expression of Sdc-3 on malignant/normal tissue based on TCGA database." (PMID 33117401, 2020). "Therefore, future studies into the regulatory mechanisms governed by the syndecan-4/syntenin-1 complex may provide new insights into the metastatic potential of melanoma, possibly paving the way for the development of novel therapies aimed at reducing the metastasis of melanoma cells." (PMID 27830760, 2016). "The data summarized in this review demonstrate that high expression of syndecan-4 is an unfavorable biomarker for estrogen receptor-negative breast cancer, glioma, liver cancer, melanoma, osteosarcoma, papillary thyroid carcinoma and testicular, kidney and bladder cancer." (PMID 33810567, 2021). "Finally, syndecan-4 overexpression significantly reduces the migration of A375 melanoma cells, whereas its siRNA knockdown enhanced their migration, consistent with the observation that syndecan-4 overexpression reduced lung and popliteal lymph node metastasis of B16F10 melanoma cells in mice." (PMID 33810567, 2021).
melanoma (continued). "Consistent with this, the overexpression of syntenin-1 but not its mutants rescued the syndecan-4-mediated reduction in the migration of A375 melanoma cells and human melanocytes, suggesting that the syndecan-4/syntenin-1 interaction is important for melanoma cell migration." (PMID 27830760, 2016). "SDC4 mRNA is expressed at high levels in almost all primary tumor entities, as opposed to ENPP2 mRNA whom highest levels could be found in renal cancers and melanoma, two cancer types that were not addressed in our study." (PMID 30237860, 2018).
hepatocellular carcinoma (16 papers, 2008 to 2024). A malignant tumor that arises from hepatocytes. "Studies have indicated that the function of SDC4 is highly associated with human tumorigenesis and development such as hepatocellular cancer, colorectal cancer, and ovarian cancer." (PMID 39218967, 2024). "Finally, association of the chemokine SDF-1 with syndecan-4 increases the resistance of hepatoma cells to TNF-alpha-induced apoptosis." (PMID 33810567, 2021). "According to a previous study, SDC4 plays a pivotal role in cell adhesion and migration and is a promising therapeutic target in hepatocellular carcinoma." (PMID 39107908, 2024). "In hepatocellular carcinoma, SDC4 can interact with the actin cytoskeleton to facilitate the assembly of focal adhesions, ultimately leading to proliferation and metastasis of tumor cells." (PMID 36816373, 2023). "for the first time identified SDC4 as a direct anti-hepatocellular carcinoma (HCC) cellular target of bufalin in inhibiting cell proliferation, invasion, and angiogenesis." (PMID 35757722, 2022). "In hepatocellular carcinoma, SDC4/DDX23 axis played a crucial role in driving cell proliferation and migration." (PMID 34966670, 2021). "For example, syndecan-4 affects hepatoma and HeLa cell motility and invasion by facilitating signaling via chemokines such as RANTES/CCL5 and SDF-1, which is in accordance with the role of heparan sulfate in chemokine signaling." (PMID 33810567, 2021). "SDC4 is essential in RANTES/CCL5-mediated hepatoma cell invasion and migration and its binding to the cell plasma membrane." (PMID 34282767, 2021). "Langerin expression abrogated HCV infection in HCV permissive cells, whereas langerin expression on the Syndecan 4 expressing cell line strongly decreased HCV transmission to a target hepatoma cell line." (PMID 32292405, 2020). "Ectopic expression of langerin on the Syndecan 4 expressing cell line enhanced HCV capture but decreased HCV transmission to a target hepatoma cell line Huh 7.5." (PMID 32292405, 2020). "Taken together, our results indicate that HCV infection is mediated by basic residues within HSPG-BD of apoE interacting primarily with SDC4 on the surface of hepatoma cells." (PMID 24751902, 2014). "Up-regulation of syndecan-4 has also been noted in hepatocellular carcinomas and malignant mesotheliomas." (PMID 25549223, 2014). "SDC4 is involved in regulating tumor cell migration in both hepatocellular carcinoma and BC." (PMID 38002057, 2023). "Notably, studies in a susceptible mouse model of Moloney murine leukemia, virus infection demonstrated that provirus integration at a site upstream of the first exon of the syndecan-4 gene resulted in particularly fast-growing hepatocellular carcinomas." (PMID 33810567, 2021). "Moreover, syndecan-4 plays an important coreceptor role in the effects of the chemokine SDF-1 on human hepatoma cell growth, migration, and invasion." (PMID 33810567, 2021). "Downregulation of SDC4 and RAB27A in human hepatocellular carcinoma (HCC) samples with CTNNB1 mutations." (PMID 39008536, 2024). "Here, SDC4 was identified as a direct cellular target of small-molecule bufalin with anti-hepatocellular carcinoma (HCC) activity." (PMID 33990545, 2021). "Even though this study is conducted with hepatoma cell lines, Syndecan 4 is also expressed by other cells including primary hepatocytes and thereby its specific ability to transmit HCV might also be involved in virus spread in the liver via hepatocytes in vivo." (PMID 32292405, 2020). "In both hepatocellular carcinoma (HCC) and cholangiocarcinoma, increased levels of syndecan-4 were found." (PMID 33810567, 2021). "SDC4 is also involved in the RANTES/CCL5 signaling and is necessary in RANTES/CCL5-induced invasion and migration of hepatoma cell lines." (PMID 34282767, 2021).
hepatocellular carcinoma (continued). "DDX23, as a substrate protein, was reported to interact with SDC4 with the aid of bufalin, a small molecule anticancer drug, to induce inactivated matrix metalloproteinases and elevated p38/JNK MAPKs phosphorylation in hepatocellular carcinoma." (PMID 36977668, 2023). "SDC4 is essential for SDF-1 (CXCL12) induced migration and invasion of hepatoma cells." (PMID 34282767, 2021). "Moreover, SDC4 is essential for CXCL12-induced migration and invasion of hepatoma cells and human cervix carcinoma (HeLa) cells." (PMID 34282767, 2021).
myocardial infarction (14 papers, 2011 to 2025). Gross necrosis of the myocardium, as a result of interruption of the blood supply to the area, as in coronary thrombosis. "Shed syndecan-4 has also been shown to associate with myocardial infarction in women only." (PMID 40977892, 2025). "A previous study indicated that the Sdc4-deficient mice exhibited reduced ECM protein deposition in the damaged region following myocardial infarction, suggesting that SDC4 may regulate scar formation in vertebrates." (PMID 38700644, 2024). "Following myocardial infarction, syndecan-4 KO mice exhibit greater impairment of cardiac function and increased mortality due to cardiac rupture." (PMID 40977892, 2025). "Additionally, shedded syndecan-4 has been found to associate with myocardial infarction (MI) incidence in women." (PMID 36092718, 2022). "Decorin and lumican are increased in myocardial fibrosis following pressure overload or myocardial infarction, while syndecan-4 contributes to myofibroblast differentiation in these settings." (PMID 32731636, 2020). "Increased syndecan-4 levels were previously detected after acute myocardial infarction and in subjects with heart failure." (PMID 29232393, 2017). "Circulating syndecan-4 concentrations are increased after acute myocardial infarction and also in heart failure, inversely correlated with left ventricular ejection fraction, suggesting a possible role as a predictive biomarker of cardiovascular events." (PMID 29232393, 2017). "Syndecan-4 has been reported to promote hypertrophic response after myocardial infarction, and its level is elevated after myocardial infarction with a peak concentration corresponding to the repair phase." (PMID 27685148, 2016). "In conclusion, dysregulation of SDC4 expression or function may contribute to the pathogenesis of conditions such as atherosclerosis, hypertension, and myocardial infarction." (PMID 39164788, 2024). "In an epidemiological study, syndecan-4 shedding was related to myocardial infarction in women." (PMID 34242246, 2021). "The literature suggests that high peaks of Sdc4 are found in plasma of patients with acute myocardial infarction, and there is increased expression in repaired areas of injured cardiac tissue, suggesting that Sdc4 is overexpressed under pathological conditions." (PMID 33211705, 2020). "Syndecan-4 is upregulated in hearts of patients and mice with pressure overload, myocardial infarction (MI), or infection." (PMID 37189684, 2023). "It has been demonstrated that syndecan-4 may play a role in collagen cross-linking, left ventricle stiffness, and cardiac fibrosis, and is involved in cardiac injury and repair, including granulation tissue formation, and neorevscularization after myocardial infarction." (PMID 27685148, 2016). "Although the loss of syndecan-4 yields no overt phenotype in the male heart at baseline, its mRNA expression and protein levels increase upon biomechanical stress or cardiac injury such as pressure overload and myocardial infarction (MI)." (PMID 38891079, 2024). "Existing studies highlighted the significant role of SDC4 as a potential marker for myocardial infarction, nonalcoholic fatty liver disease, and endothelial dysfunction in patients with resistant hypertension." (PMID 36199068, 2022). "We have previously shown increased myocardial mRNA expression of all four members of the syndecan family and increased protein levels of syndecan-4 in the hypertrophic non-infarcted region of the left ventricle following myocardial infarction." (PMID 22164265, 2011).
osteoarthritis (13 papers, 2015 to 2025). A noninflammatory degenerative joint disease occurring chiefly in older persons, characterized by degeneration of the articular cartilage, hypertrophy of bone at the margins and changes in the synovial membrane. "A strong positive correlation between Mmp9 and shed Sdc4 has been identified in the synovial fluid of osteoarthritis patients, while inhibition or knockdown of Mmp9 reduces Sdc4 shedding." (PMID 40180176, 2025). "Moreover, an increased expression of some of the HS core proteins in osteoarthritis, including perlecan, syndecan 1, or syndecan 4 has been shown." (PMID 38136608, 2023). "In osteoarthritis, nMMP-9-mediated syndecan-4 shedding correlates with severity." (PMID 36267087, 2022). "We identify syndecan-4 as a downstream molecular target of LRP3 in osteoarthritis pathogenesis." (PMID 36414669, 2022). "Although SDC1 has been extensively studied for its shedding and use as a biomarker for several diseases, shedding of SDC4 has been previously shown as an important regulator in pathologies such as cardiac dysfunctions, diabetes mellitus, osteoarthritis, and cancer." (PMID 39764382, 2024). "SDC4 (Syndecan-4), a target of miR-140-3p.2 but not miR-140-3p.1, has been implicated in osteoarthritis progression through activation of ADAMTS5, suggesting SDC4 suppression by miR-140-3p.2 may maintain a healthy cartilage phenotype." (PMID 32660984, 2020). "As a result, using a syndecan-4-specific antibody inhibits the activation of ADAMTS-5, thereby slowing the progression of osteoarthritis." (PMID 34868573, 2021). "Syndecan-4 has been targeted or utilized as part of therapeutic approaches in nonmalignant diseases, and this knowledge could be utilized in a cancer context in the future: For example, antibody-mediated inhibition of syndecan-4 has been proposed as a treatment for osteoarthritis." (PMID 33810567, 2021).